IL36B (interleukin 36 beta)
Description:
Cytokine that binds to and signals through the IL1RL2/IL-36R receptor which in turn activates NF-kappa-B and MAPK signaling pathways in target cells linked to a pro-inflammatory response. Part of the IL-36 signaling system that is thought to be present in epithelial barriers and to take part in local inflammatory response; similar to the IL-1 system with which it shares the coreceptor IL1RAP. Stimulates production of interleukin-6 and interleukin-8 in synovial fibrobasts, articular chondrocytes and mature adipocytes. Induces expression of a number of antimicrobial peptides including beta-defensins 4 and 103 as well as a number of matrix metalloproteases. Seems to be involved in skin inflammatory response by acting on keratinocytes, dendritic cells and indirectly on T-cells to drive tissue infiltration, cell maturation and cell proliferation. In cultured keratinocytes induces the expression of macrophage, T-cell, and neutrophil chemokines, such as CCL3, CCL4, CCL5, CCL2, CCL17, CCL22, CL20, CCL5, CCL2, CCL17, CCL22, CXCL8, CCL20 and CXCL1, and the production of pro-inflammatory cytokines such as TNF, IL-8 and IL-6.
Synonyms: IL-1F8; IL-1H2; IL1F8; IL1H2; FIL1; FILI-(ETA); IL1-ETA; MGC126880; MGC126882; FIL1-(ETA); FIL1H
Tractability: Antibody: UniProt places it where antibodies can reach, with high confidence; its Gene Ontology location is reachable by antibodies, with high confidence.
Gene: Protein-coding gene on chromosome 2 (113,022,089 to 113,052,867, reverse strand). Ensembl gene ENSG00000136696.
Subcellular location: Cytoplasm; Secreted
Pathways (Reactome):
Immune System: Interleukin-36 pathway
Gene Ontology:
Molecular function: cytokine activity; interleukin-1 receptor binding
Biological process: cellular response to lipopolysaccharide; cytokine-mediated signaling pathway; immune response; inflammatory response; positive regulation of T cell differentiation
Cellular component: cytoplasm; extracellular region
Genetic constraint (gnomAD): Loss-of-function variants: 17 observed, 14.75 expected, observed/expected ratio (o/e) 1.15, 90% interval 0.79 to 1.7. The upper end of that interval is the gene's LOEUF score, 1.7, which puts it in group 6 of 6, group 1 being the genes least tolerant of losing a copy. Missense variants: 165 observed, 157.07 expected, observed/expected ratio (o/e) 1.05, 90% interval 0.93 to 1.2. Synonymous variants: 44 observed, 49.42 expected, observed/expected ratio (o/e) 0.89, 90% interval 0.7 to 1.14.
Homologues: Orthologues: macaque IL36B (88% identical), rat Il36b (66% identical), dog IL36B (65% identical), mouse Il36b (61% identical), zebrafish il1b (27% identical), zebrafish il1fma (17% identical). Paralogues in human: IL36A (45% identical), IL36G (43% identical), IL37 (30% identical), IL1B (29% identical), IL36RN (29% identical), IL1RN (28% identical), IL1F10 (24% identical).
Diseases named in the same sentence as IL36B in open-access papers:
IL36B is named in the same sentence as 20 diseases in open-access papers, as found by Europe PMC text mining. Sharing a sentence is not in itself a finding about the gene and the disease. The quoted sentences say what the papers report.
psoriasis (11 papers, 2012 to 2023). An autoimmune condition characterized by red, well-delineated plaques with silvery scales that are usually on the extensor surfaces and scalp. "The pro-inflammatory properties of IL36B have been implicated in the pathogenesis of psoriasis, a common disease characterized by scaly rashes on the skin." (PMID 36519529, 2022). "IL-17 elicits its pro-inflammatory effects in RHE, stimulating the expression of several genes including IL23A, IL1β, and IL36B (IL1F8) that have been implicated in psoriasis pathogenesis and found to be over-expressed in psoriatic lesional skin." (PMID 24587313, 2014). "Molecular analysis of the skin of IgG- and anti-IL36R-treated K14-IL17Aind mice revealed effective suppression of psoriasis-associated cytokines (Il36a, Il36g, Il36b, Il23a, and Tnf), chemokines (Cxcl1, Cxcl5, and Ccl2) and antimicrobial-peptides (such as Defb4) on mRNA level." (PMID 38162658, 2023). "We then investigated whether PCSK9 is linked to other potential inflammatory mediators of psoriasis in addition to IL36B and IL36G." (PMID 35862195, 2022). "The strong link between ELOVL4 and IL36B, CDK7, CHMP2B, and S100A13 was also evident in RNA-Seq data sets of psoriasis lesional skin." (PMID 35900871, 2022). "IL36B and IL36G are both in the core set of DEGs and highly up-regulated in each form of psoriasis." (PMID 30054515, 2018).
osteoarthritis (3 papers, 2006 to 2022). A noninflammatory degenerative joint disease occurring chiefly in older persons, characterized by degeneration of the articular cartilage, hypertrophy of bone at the margins and changes in the synovial membrane. "In agreement with this, IL-36A and IL-36B abundance were significantly elevated in serum of rheumatoid arthritis patients compared with healthy CTLs, and IL-36A was also elevated in synovial tissues from rheumatoid arthritis patients as compared with osteoarthritis patients." (PMID 29434599, 2018).
psoriasis vulgaris (1 paper, 2023). Plaque psoriasis is the most common presentation of psoriasis. "IL-36 receptor expression (encoded by IL1RL2), as well as the expression of IL36A, IL36B, and IL36G are significantly upregulated in psoriasis vulgaris skin lesions, compared to healthy and non-lesional skin samples." (PMID 38162658, 2023).
rosacea (1 paper, 2023). A chronic erythematous skin disorder that affects the face. "Among innate cytokines, we observed a significant increase in TNF, IL1B, IL8, IL12B, IL23A, and IL10 — but not IL36B — in rosacea skin lesions as compared with skin from healthy donors." (PMID 36633910, 2023).
bacterial infection (2 papers, 2016 to 2023). "The downregulated proteins were related to the reduction in markers of inflammation (e.g., Alox5, Lbp, C5, Il36b, and Mmp8) and bacterial infections (e.g., Masp2, Mbl1, Krt34, and Cfd)." (PMID 38030636, 2023).
infection (1 paper, 2019). The state of being infected such as from the introduction of a foreign agent such as serum, vaccine, antigenic substance or organism. "We found that the expression of eight genes, including Il18, Il36b, Il17rc, Tnfsf10, Tnfsf11, Tnfsf14, Tnfsf15, and Il1a, were closely correlated with the severity of HAdV-55 infection." (PMID 30787914, 2019).
IL36B also shares sentences with these, for which no sentence is quoted: atherosclerosis (2 papers); inflammatory skin disease (2); rheumatoid arthritis (2); Arthritis (1); asthma (1); breast carcinoma (1); cardiac hypertrophy (1); cerebral malaria (1); Erythema (1); ichthyosis (1); liver inflammation (1); lung carcinoma (1); psoriatic arthritis (1); tumor (1).